VTN (vitronectin)
Diseases named in the same sentence as VTN in open-access papers (continued):
Sharing a sentence is not in itself a finding about the gene and the disease.
gastric cancer (10 papers, 2019 to 2025). A primary or metastatic malignant neoplasm involving the stomach. "Further survival analysis showed that THBS1, SERPINE1, and VTN were significantly associated with the prognosis of gastric cancer." (PMID 35372476, 2022). "In gain- and loss-of function analysis in gastric cancer cells, VTN was further verified in consistent with VEGFR2 in expression levels and in regulating cell growth and motility in vitro and in vivo." (PMID 30819137, 2019). "In summary, our data indicated that higher levels of VEGFR2 and its target VTN in cancer specimens were associated with aggressiveness and poorer prognosis of gastric cancer." (PMID 30819137, 2019). "Beyond its angiogenic role, VEGFR2 contributes directly to gastric cancer tumorigenesis: overexpression in tumor cells promotes proliferation, migratory capacity, and xenograft tumor growth, in part through upregulation of vitronectin (VTN), a factor associated with adverse clinical outcomes." (PMID 41227318, 2025). "This phenomenon may be relevant for the development of gastric pathologies, given the central role of uPAR in plasminogen-mediated extracellular matrix remodeling, vitronectin-dependent cell adhesion and migration, and its upregulation in gastric cancer and associated prognostic impact." (PMID 32660136, 2020). "We then evaluated expressions of VTN in gastric cancer cell lines and identified a similar expression trends as VEGFR2 in both protein and mRNA levels." (PMID 30819137, 2019). "In 156 gastric cancer patients, VTN act as a poor prognostic factor both for disease-free survival and overall survival (P = 0.043 and 0.040), in consisting with the data obtained from Kaplan-Meier Plotter datasets." (PMID 30819137, 2019). "VEGFR2/VTN axis in gastric cancer cells may be involved in tumorigenesis and metastasis in a pro-angiogenic-independent way although the precise mechanisms need to be further elucidated." (PMID 30819137, 2019). "To confirm whether VTN could be a pro-oncogenic executor, we investigated the relationship between VTN expression and biological function of gastric cancer cells." (PMID 30819137, 2019). "Invasion of gastric cancer cells could be repressed by knockdown but could be accelerated by overexpression of VTN." (PMID 30819137, 2019). "Hence, VEGFR2 and VTN expression in cancer tissues may also serve as biomarkers for tumorigenesis and metastasis of gastric cancer and as direct therapeutic targets in cancer cell level for traditional anti-angiogenesis treatment." (PMID 30819137, 2019). "Moreover, in gastric cancer samples, VTN was as also revealed as a poor prognostic factor." (PMID 30819137, 2019). "Moreover, both in vitro and in vivo growth of gastric cancer cells could be inhibited by knockdown but could be promoted by overexpression of VTN." (PMID 30819137, 2019). "Next, to verify the effect of macrophages on the adhesion and invasion of gastric cancer cells, the adhesion of AGS cells to the extracellular matrix (ECM) proteins, such as vitronectin, collagen, and fibronectin, was examined." (PMID 36613819, 2022). "With respect of association of gastric cancer and VTN, only one document revealed that VTN acted as the downstream molecule of CEP65, which may provide gastric cancer cells with capacity to detach from the ECM, decreasing cell adhesion." (PMID 30819137, 2019).
glioblastoma (10 papers, 2009 to 2025). The most malignant astrocytic tumor (WHO grade IV). "Vitronectin (VTN) emerged as the highest-ranking ECM component in the cell surface proteomic analysis of adult glioblastoma, highlighting its potential role in tumor progression, adhesion, and immune modulation." (PMID 40517137, 2025). "For example, cultured glioblastoma cells can generate basement membrane components, such as Laminin, Vitronectin, Fibronectin, Tenascin C, Collagen I, Collagen IV, or Collagen VI." (PMID 35053605, 2022). "ITGB3 has been reported to be recruited to the membrane and to regulate invasion in hypoxia in glioblastoma by interacting with type III EGF receptor (EGFRvIII) in a hypoxic microenvironment enriched with vitronectin." (PMID 29383126, 2017). "The results of this study indicated that such triggering is via specific mediation of extracellular matrix proteins, particularly fibronectin and vitronectin synthesized and secreted by glioblastoma cells." (PMID 25963312, 2015). "Thus, the migratory promoting effect of MGP on glioblastoma cell lines might be mediated by both BMPs and vitronectin." (PMID 19712474, 2009). "In addition, MGP effects on glioblastoma cell migration might be mediated by binding of MGP to vitronectin." (PMID 19712474, 2009). "On the other hand, glioblastoma cell lines with knockdown of PAI1 showed decreased dispersal, and inhibited migration and movement on both uncoated and vitronectin coated surfaces." (PMID 39859388, 2025). "For example, it has been reported that ECM proteins (laminin, fibronectin, and vitronectin) mediated cell adhesion‐mediated drug resistance (cilengitide, an integrin inhibitor, and/or carmustine, an alkylating chemotherapy) in glioblastoma (GBM)." (PMID 37229486, 2023). "Glioblastoma dissemination routes, such as myelinated axon fibers, and vascular basement membrane and externa contain a specific ECM composition, including fibrous proteins, such as Collagens, Fibronectin, Laminins, and Vitronectin." (PMID 35053605, 2022). "Similarly, when glioblastoma multiforme cells are treated with the phorbol ester PMA, NF-κB induces the expression of αVβ3 Integrin along with fibronectin and vitronectin." (PMID 28962574, 2017). "The mechanisms linking MGP knockdown and reduced migration of glioblastoma cells remain to be determined, but based on available evidence it is conceivable that interactions with members of the bone morphogenetic protein (BMP) family and the ECM component vitronectin are involved." (PMID 19712474, 2009).
amyloidosis (9 papers, 2018 to 2025). A disorder characterized by the localized or diffuse accumulation of amyloid protein in various anatomic sites. "Clusterin, known to interact and mediate the clearance of Aβ, and Vitronectin have both already been associated with various subtypes of amyloidosis." (PMID 35008745, 2021). "It is noteworthy that non‐amyloidosis‐associated proteins reported in human cases of AApoAIV amyloidosis such as vitronectin, serum albumin, clusterin, collagen alpha‐2 (I) chain, collagen alpha‐1 (I) chain, and actin 48 were also found in our samples." (PMID 29774542, 2018). "This contrasts with the partial correspondence of SAP in AA amyloidosis and Apo A4 and Apo E in ATTR amyloidosis in our study, indicating the importance of VTN as an extracellular component involved in amyloid pathology." (PMID 36240260, 2022). "By mass spectrometry three amyloid signature proteins were also identified: vitronectin, apolipoprotein A-IV and apolipoprotein A-I in 6/7 (85.71%), 4/7 (57.14%), and 3/7 (42.86%) cases, respectively, contributing with new knowledge about the amyloid proteome of amyloidosis in wild avian species." (PMID 40892784, 2025). "To evaluate the applicability of this method in the study of amyloid genesis, we also investigated associated proteins that are frequently observed in amyloid deposition, such as serum amyloid P (SAP), apolipoprotein A4 (Apo A4), apolipoprotein E (Apo E), and vitronectin (VTN)." (PMID 36240260, 2022). "Besides these, other proteins like ApoAIV, ApoE, APC, and vitronectin, the well-known components of the so called “universal amyloid proteome” in systemic amyloidosis, were all identified in our localized amyloidosis cases with much higher intensities than the former three." (PMID 31531279, 2019). "In this study, VTN-derived peptides were detected in all AA and ATTR amyloidosis cases, and their localization corresponded to amyloid deposition." (PMID 36240260, 2022). "APOE and VTN are generally not regarded as causative amyloidogenic proteins, and consequently, there is no recognized APOE or VTN amyloidosis as defined by the latest classification of the ISA." (PMID 40701201, 2025). "Additional “peaks”, primarily among the amyloid signature proteins APOA4, APOE and VTN have been reported before, but should not be misinterpreted as indicative of mixed amyloidosis." (PMID 40701201, 2025).
Stroke (8 papers, 2009 to 2023). Sudden impairment of blood flow to a part of the brain due to occlusion or rupture of an artery to the brain. "In AAV‐VTN infected female VTN−/− mice, stroke caused a 3‐fold increase in plasma VTN levels at 24 h after MCAO, as shown by ELISA." (PMID 35531929, 2022). "Thus, the increase in liver and plasma VTN protein after stroke is most likely caused by increased protein translation and release, respectively." (PMID 35531929, 2022). "A recent study on induced strokes in mice found the leakage of vitronectin into the brain to be detrimental but in female mice only." (PMID 37175625, 2023). "The in vitro data showing acetylcholine inhibition of VTN synthesis and release by hepatocytes through M1 muscarinic receptors was confirmed in vivo by showing that the M1/3 agonist, bethanechol, reduced plasma VTN levels after the MCAO stroke." (PMID 35531929, 2022). "Our data showing stroke‐induced high plasma VTN levels in VTN−/− females with VTN overexpressed only in hepatocytes suggest that hepatocytes in the liver are the sole sources of the increase in wildtype females." (PMID 35531929, 2022). "Longitudinal post-stroke blood proteomics profiles suggest that the alternative pathway of complement activation remains in a state of higher activation from 3-7 days to 3 months post-stroke, while simultaneously being regulated by clusterin and vitronectin." (PMID 32849183, 2020). "We wanted to define the unknown regulation mechanism of VTN induction after stroke in female mice as this might help to identify molecular targets to dampen the harmful increase." (PMID 35531929, 2022). "In conclusion, we provide evidence in females that liver and plasma VTN protein levels are suppressed by M1 receptor cholinergic signaling on hepatocytes and that increased VTN expression in the blood after stroke is produced by the liver, most likely via vagal innervation." (PMID 35531929, 2022). "The increased VTN‐driven inflammation seen in the female mouse injured brain would also be consistent with the findings that the vagus nerve has anti‐inflammatory activity in a number of disease models, including stroke." (PMID 35531929, 2022). "It will be important to determine whether sexually dimorphic vagal nerve activity plays a role in stroke and possibly other disorders with known increased plasma VTN levels." (PMID 35531929, 2022). "It was found that VTN protein expression is higher in stroke patients’ platelets." (PMID 27336623, 2016). "We also tested other organs known to produce VTN, but VTN mRNA was not affected by the stroke in the stomach, jejunum, colon, kidney, lung or heart." (PMID 35531929, 2022). "Together, this suggests that VTN protein translation and/or release, and not transcription, is responsible for the stroke‐induced increases in liver and blood VTN in females." (PMID 35531929, 2022). "This suggests that surgery may itself contribute to VTN mRNA changes but that VTN protein translation and/or release is dependent on the MCAO stroke." (PMID 35531929, 2022). "Fluid phase identification of inactive pre-MAC complexes with protein S such as sC5b-7, 8 and 9 in addition to VTN and CLU may also provide further information on the regulatory activity of the MAC in stroke survivors." (PMID 32849183, 2020). "The finding that liver and plasma VTN protein increased in these mice after stroke without an increase in hepatocyte Serpina 1A mRNA in the liver is consistent with the finding that VTN mRNA in the liver of wildtype females is not increased either compared to shams." (PMID 35531929, 2022). "However, adhesion events were markedly increased following the introduction of arginine-glycine-aspartate (RGD)-labelled synthetic MPs or endogenously-derived EVs from experimental stroke animals carrying excess RGD proteins, including vitronectin, CD40-ligand and thrombospondin-1." (PMID 31676801, 2019).
atherosclerosis (7 papers, 2008 to 2024). A disease characterized by the build-up of fatty material and calcium deposition in the arterial wall resulting in partial or complete occlusion of the arterial lumen. "Vitronectin has been identified in deposits associated with AD, atherosclerosis, systemic amyloidoses, and glomerulonephritis." (PMID 18939994, 2008). "GPVI-Fc binds to collagen and protects against atherosclerosis but also binds to activated endothelium mainly via vitronectin to prevent platelet-endothelial interactions after I/R." (PMID 38274818, 2023). "Our study establishes that VTN regulates cholesterol‐driven atherosclerosis and inflammation in the local milieu of the arteries, establishing a pivotal role of VTN in the pathogenesis of CAD." (PMID 35141476, 2022). "The role of vitronectin (VTN), a major cell attachment glycoprotein, in the pathogenesis of atherosclerosis remains elusive." (PMID 35141476, 2022). "Increased tissue vitronectin is observed in diseases of altered blood flow, including atherosclerosis, myocardial infarction, and cancer." (PMID 28659710, 2017). "We suggest that serum levels of Vitronectin, MDA and hs-CRP increased in CAD subjects and potentially represent a pathogenic factor for atherosclerosis." (PMID 26430499, 2015). "The multifunctional protein vitronectin is present within the deposits associated with Alzheimer disease (AD), age-related macular degeneration (AMD), atherosclerosis, systemic amyloidoses, and glomerulonephritis." (PMID 18939994, 2008). "We establish that, VTN plays a pivotal role in cholesterol‐driven atherosclerosis and aortic inflammation and might be a useful indicator for atherosclerotic plaque burden and stability." (PMID 35141476, 2022). "In addition, VTN interactions with platelets integrin Gp2b/3a triggers VTN dependent platelets adhesion that can lead to thrombus formation of atherosclerosis." (PMID 27336623, 2016). "Our results put forth the possibility that vitronectin misfolding and amyloid formation may contribute to age-related diseases such as atherosclerosis, AMD, and AD." (PMID 18939994, 2008). "In addition, serum levels of vitronectin are elevated in patients with atherosclerosis, type 2 diabetes, and Alzheimer disease (AD)." (PMID 18939994, 2008). "However, there are no reports regarding the functional involvement of VTN in pathological atherosclerosis in the literature." (PMID 35141476, 2022).
Cirrhosis (7 papers, 2014 to 2025). A chronic disorder of the liver in which liver tissue becomes scarred and is partially replaced by regenerative nodules and fibrotic tissue resulting in loss of liver function. "Vitronectin is known to be decreased in serum during liver conditions such as fatty liver, steatohepatitis, fibrosis, and cirrhosis." (PMID 37414249, 2023). "Furthermore, the vitronectin level was inversely correlated with the severity of cirrhosis." (PMID 24968805, 2014). "Additionally, ligand–receptor pairs such as SPP1–ITGAV, VTN–ITGAV, and HLA-related interactions were more active in cirrhosis, suggesting their potential roles in macrophage polarization, immune evasion, and tumor cell adhesion or migration." (PMID 41153430, 2025). "Plasma proteome profiling of 48 patients with and without cirrhosis or NAFLD revealed six statistically significantly changing proteins (ALDOB, APOM, LGALS3BP, PIGR, VTN, and AFM), two of which are already linked to liver disease." (PMID 30824564, 2019). "The plasma vitronectin level was low in all liver disease groups as compared with that in the healthy controls, although the difference was only significant between the controls and patients with HCC and decompensated cirrhosis." (PMID 24968805, 2014).
osteosarcoma (7 papers, 2006 to 2025). A usually aggressive malignant bone-forming mesenchymal neoplasm, predominantly affecting adolescents and young adults. "A cell adhesion inhibitory analysis was performed by pre-incubating human osteosarcoma MG63 cells with various PP peptides before seeding onto vitronectin." (PMID 25396425, 2014). "A number of studies have reported that Ech is a potent antagonist of integrins αvβ3, αIIbβ3, and α5β1 for cancer therapy and inhibits HUVEC adhesion to immobilized fibronectin and vitronectin, as well as cell proliferation, migration, invasion, and adhesion of metastatic human osteosarcoma." (PMID 33182321, 2020). "Interestingly, the data illustrate that approximately 1000-times higher concentrations of cilengitide are needed to detach the here investigated osteosarcoma cell lines from vitronectin than to inhibit their de novo adhesion to vitronectin." (PMID 27409827, 2016). "Because vitronectin induced the haptotaxis migration of osteosarcoma MG63 cells and dental pulp fibroblastic cells, DPSCs were also seeded onto the vitronectin-coated Boyden chamber." (PMID 37730838, 2023). "Since rPP was incapable of aiding cell adhesion to human osteosarcoma MG63 cells or mouse pre-osteoblastic MC3T3-E1 cells, we examined various cell adhesions on rPP in parallel with rC-DMP-1 and vitronectin with the addition of MnCl2." (PMID 25396425, 2014). "Detachment experiments carried out in serum-containing medium showed that cilengitide detached the osteosarcoma cells at comparable concentrations from non-coated or vitronectin-coated plastic." (PMID 27409827, 2016).
age-related macular degeneration (6 papers, 2008 to 2024). Age-related loss of vision in the central portion of the retina (macula), secondary to retinal degeneration. "In addition, we and others have observed vitronectin reactivity in all drusen samples analyzed, which are extracellular ocular deposits associated with aged eyes and eyes with age-related macular degeneration." (PMID 18939994, 2008). "VTN is a major component of abnormal deposits associated with age-related macular degeneration (AMD), Alzheimer’s disease and other age-related diseases." (PMID 36293243, 2022). "Histologically, DLDs have been demonstrated to react with antibodies against C5, TIMP3, vitronectin, and amyloid P component, which are the markers of age-related macular degeneration (AMD)-associated drusen, thus outlining a similarity between DLD and the typical drusen seen in patients with AMD." (PMID 37371724, 2023). "In the human eye, VTN is synthesized locally in the retinal pigment epithelium–choroidal complex and is involved in the pathogenesis of age-related macular degeneration (AMD)." (PMID 34445121, 2021). "The identification of vitronectin and CFH as tyrosine-sulfated proteins is significant, since both are deposited in drusen in the eyes of patients with age-related macular degeneration (AMD)." (PMID 25136834, 2014). "We recently reported that human ocular drusen contain nonfibrillar oligomers, which suggests that age-related macular degeneration may be another example of this type of amyloidosis, and a number of studies identify vitronectin as one of the most abundant drusen proteins." (PMID 18939994, 2008).
brain tumor (6 papers, 2012 to 2025). "Three substrates that are found in the brain and are typically overexpressed in brain tumors were tested: laminin, type IV collagen, and vitronectin." (PMID 32180897, 2020). "Among these ECM, fibronectin (FN) and vitronectin (VTN) were identified within primary brain tumors and upregulated within both the tumor-stroma and at advancing edge within brain parenchyma." (PMID 26717039, 2016). "Within primary brain tumors, components such as vitronectin, osteopontin, tenascin-C, SPARC and BEHAB can be found, and some of them are upregulated and modulate brain tumor growth, proliferation and invasion." (PMID 22973309, 2012).